CD4 (CD4 molecule)
Diseases named in the same sentence as CD4 in open-access papers (continued):
Sharing a sentence is not in itself a finding about the gene and the disease.
AIDS (continued). "HIV deaths are predicted to remain elevated after the period of disruption because the reduction in CD4 cell count for some individuals is assumed to lead to an increased risk of AIDS for some time after ART is reinitiated." (PMID 32673577, 2020). "The risk of AIDS for patients with CD4 cells < 350 reached statistical significance comparing to patients with ≥ 500 (P-value = .027)." (PMID 31996148, 2020). "An increased level of CD4 count is always linked with a decreased risk of a new AIDS event or death." (PMID 32257156, 2020). "Zn2+ deficiency correlates with diminished CD4+ T cells, high viral loads, AIDS, and mortality, and its supplementation delays disease progression." (PMID 33081049, 2020). "Age, WHO AIDS staging, gender and residence are relevant parameters associated with viral load decline and CD4 count in elderly PLWHA." (PMID 34394214, 2020). "Resistance to C. neoformans clearly requires CD4+ T-cells and AIDS is the most common predisposing illness, but the innate immune system also plays an important role." (PMID 32545735, 2020). "In the Bivariate analysis, brush mouth daily (oral hygiene) and CD4 cells/μl were significantly associated with oral candidiasis in HIV/AIDS patients." (PMID 32774600, 2020). "The loss of CD4+T cells is a well-established deficiency in PLWH whose HIV infection has progressed to the acquired immune deficiency syndrome (AIDS) stage." (PMID 32373548, 2020). "Both C. neoformans and C. gattii infect people, but about 95% of human infections are caused by C. neoformans C. neoformans infections cause disease primarily in people with CD4 T-cell deficiencies such as AIDS and lymphomas." (PMID 32545735, 2020). "Frailty in HIV-1 infection highly correlates with a high VL and a decline in CD4+ T cells, and the CD4/CD8 ratio has been suggested as a marker of individuals at risk of suffering from non-AIDS-related events." (PMID 32187205, 2020). "After controlling for the effect of other variables program of enrolment, WHO clinical stage, IPT, treatment failure and base line CD4 count were significantly associated with TB incidence among HIV/AIDS infected patients in the course of treatment." (PMID 32864154, 2020). "IMPORTANCE The lentivirus human immunodeficiency virus (HIV) targets and destroys CD4+ T cells, leaving the host vulnerable to life-threatening opportunistic infections associated with AIDS." (PMID 32075937, 2020). "In fact, in human immunodeficiency virus (HIV)-infected patients, the CD4 T cell number is drastically reduced, which is the main cause of acquired immunodeficiency syndrome (AIDS)." (PMID 33126494, 2020). "This can lead to impaired CD4+ T-cell generation and contributes to the loss of peripheral CD4+ T cells and the manifestation of AIDS." (PMID 30862061, 2019). "IL-2 production declines and IL-2-producing T cells is impaired in chronically HIV-1-infected patients, as indicated by loss of CD4+ T cells and progression to AIDS." (PMID 31379845, 2019). "Human immunodeficiency virus (HIV), the causative agent of acquired immune deficiency syndrome (AIDS), destroys the host immune system by invasion and subsequent destruction of CD4+ lymphocytes, leading to death by opportunistic infections." (PMID 31052477, 2019). "HIV-1, the causative agent of AIDS, mainly infects CD4+ T cells and macrophages and triggers the IFN-I-mediated signaling cascade." (PMID 30915053, 2019). "Higher CD4 levels (⩾200 cells/μl) were beneficial for all causes, whereas a higher CD4 nadir (⩾350 cells/μl) was beneficial only for AIDS-defining events (HR 0.39)." (PMID 30869037, 2019). "The furher results showed that raising animal and drinking un-boiled water were the risk factors for Blastocystis infection among HIV/AIDS cases, and the new variable CD4+ T*HIV was also contribution the Blastocystis prevalence." (PMID 31623666, 2019).
AIDS (continued). "Human immunodeficiency virus type 1 (HIV-1), the causative agent of AIDS, targets cells that express CD4, such as CD4+ T cells and macrophages, for its infection." (PMID 30915053, 2019). "Analysis of continuous CMV IgG levels and risk of non-AIDS events also showed a significant association (OR = 1.58 [95% CI: 1.12, 2.24], P = 0.01) that was maintained after adjusting for CD4 count." (PMID 30815626, 2019). "Nevertheless, there were significant associations between GWG variant and the CD4 count (P < .05) and time of AIDS (P < .05) in HIV mono-infected patients." (PMID 31335686, 2019). "Early ART initiation (amongst patients with CD4 cell counts ≥500 cells per μL) was associated with a 94% reduction in the risk of AIDS death during the first six months compared with starting at < 200 cells per μL." (PMID 30819120, 2019). "Subtype 2b and genotype 5 were already related to higher rates of CD4+ T-cells compared to subtype 2a and genotype 1, and genotype 7 has already been associated with slower progression to AIDS." (PMID 31309117, 2019). "The analysis showed that although CD4+ T-cell level and decline were independently associated with progression to AIDS, the effect size was largest for the CD4% level or the combined CD4% level/decline stratifications." (PMID 30622192, 2019). "Most patients present with extensive tumour combined with low CD4 counts and systemic illness, or poor risk disease based on the AIDS Clinical Trials Group (ACTG) staging criteria." (PMID 31516547, 2019). "Starting treatment early (CD4 cell counts ≥500 cells per μL) significantly reduced the risk of AIDS death in the first six months of treatment and this survival benefit is greatest in women, younger age groups and people living in the North region." (PMID 30819120, 2019). "Currently, the risk of non-AIDS events appears to be properly identified by using some surrogate markers such as the CD4/CD8 ratio and the VACS index." (PMID 30818365, 2019). "Univariate analysis demonstrated that mode of HIV exposure (p < 0.001), HCV co‐infection (p = 0.027), cohort group (p < 0.001), diabetes (p = 0.014), BMI, CD4, RNA and calendar year (all p < 0.001) were associated with AIDS‐related mortality." (PMID 30615271, 2019). "Our findings are similar to results of these studies, demonstrating lower CD4 cell counts and older age as independent risk factors for both AIDS and non‐AIDS mortality." (PMID 30615271, 2019). "The CD4+ T-cell counts reflect the level of immune suppression; and when CD4+ T-cells fall below 350 cells/μL, the risk of death, AIDS, and/or non-AIDS-defining conditions increases." (PMID 30718554, 2019). "Consider a cohort study to estimate the effect of antiretroviral zidovudine treatment (AZT) in HIV (human immunodeficiency virus) positive individuals, on progression to AIDS (acquired immune deficiency syndrome), where CD4 count is a confounder." (PMID 31619986, 2019). "Low CD4/CD8 ratios were also independently associated with the risk of non-AIDS morbidity and mortality in virally suppressed individuals based on data from the CoRIS cohort." (PMID 31867010, 2019). "The strong association between SD and PD, and the increased risk of SD and PD in AIDS patients, are most simply explained by waning CD4+ T cell control of Malassezia populations." (PMID 31396143, 2019). "There were 48,269 adult HIV/AIDS patients with a CD4 count of less than 200/μL and thus particularly at risk of serious fungal infections due to severe immunosuppression." (PMID 31083531, 2019). "Factors associated with increased risk of AIDS‐related mortality were higher viral load, high blood glucose, low CD4 cell count and low BMI." (PMID 30615271, 2019). "Third, it has been shown that PLWH with CD4 count between 500 and 750 cells still display increased risk of AIDS compared to PLWH with higher CD4 counts." (PMID 30763363, 2019).
AIDS (continued). "Individuals with immunodeficiency, such as impaired T cell function in HIV/AIDS patients, are highly susceptible to C. neoformans infection, and the importance of CD4+ T cells in defense against cryptococcosis has been well documented." (PMID 31772051, 2019). "The infection of HIV/AIDS has been known not only to induce depletion of CD4 T-cells but also to reduce CD8 T-cells causing downmodulation, reduction in T-cell subpopulation, and defective cell mediated immunity against any microbial infection." (PMID 31354844, 2019). "Polymorphisms in IL7RA, the gene encoding for IL7Rα, have previously been associated with rapid progression to AIDS and with CD4+ T-cell recovery after initiation of cART, especially the missense polymorphism rs6897932." (PMID 31208153, 2019). "Older age, hepatitis B and C co‐infection, high blood glucose, low CD4 cell count and BMI were associated with increased non‐AIDS death." (PMID 30615271, 2019). "Specifically, even though women have lower plasma viral loads and higher CD4+ T cell counts than men, women have a higher risk of progressing to AIDS (acquired immune deficiency syndrome)." (PMID 30547182, 2019). "In Histoplasma-endemic areas, a CD4 count < 150 cells/μL places AIDS-patient at high risk of DH and is considered an indication for prophylactic treatment." (PMID 31181847, 2019). "The results showed a significant association between HIV B’ variant and CD4 count and time of AIDS in HIV mono-infected patients." (PMID 31335686, 2019). "Low CD4/CD8 ratio has also been associated with non-AIDS defining cancer in patients on antiretroviral therapy but no such association was observed in our study." (PMID 30562358, 2018). "Late presenters have delayed initiation of cART, CD4 values below 350 cells/mm3 and below 200 cells/mm3 in many cases, and higher risk of AIDS progression and death." (PMID 30522500, 2018). "Four variables (intravenous drug use as HIV transmission risk, presence of AIDS‐defining illness, baseline CD4 count, and time from HIV diagnosis to ART initiation) had missing values for some patients and were imputed for analyses." (PMID 29569354, 2018). "The mechanisms underlying CD4+ T-cells loss and AIDS progression in HIV-ECs are poorly understood and are likely to be multifactorial." (PMID 29967620, 2018). "In our previous report, we showed that HIV/AIDS patients with CD4+ cell count below 200 cells/mm3 were frequently predisposed to cryptosporidiosis." (PMID 30369995, 2018). "CD4+ T-cells are the major target for human immunodeficiency virus (HIV); therefore, a gradual CD4+ T-cells count decline and progression to acquired immune deficiency syndrome (AIDS) are normally observed during untreated HIV-infection." (PMID 29967620, 2018). "Chronic inflammation and elevated immune activation are associated with a faster progression to AIDS and CD4+ T cell depletion." (PMID 30050532, 2018). "The use of ART is recommended at any CD4 T cell count mainly in order to reduce sexual transmission, the risk of AIDS event and mother-to-child transmission of HIV9." (PMID 29872068, 2018). "The two patients who died separately had the underlying disease AIDS (CD4 count: 20 cells/μL, viral load: 21,46,000 copies/mL) and bladder urothelial carcinoma with recurrence and needed to be treated in the intensive care unit." (PMID 29666665, 2018). "HIV-1 actively replicates in CD4+ T lymphocytes, causing progressive cell loss and leading to the development of AIDS." (PMID 30206166, 2018). "Previous reports have characterized immune activation during HIV-1 infection and attempted to determine the relationship with CD4+ T-cells loss and AIDS progression." (PMID 29967620, 2018). "The incidence of HIV and AIDS related deaths is due to a continuous immunodeficiency associated with the depletion of CD4+ T lymphocytes, which leads to a compromised immune system." (PMID 29795558, 2018).
AIDS (continued). "The findings of this study show that double deletion of glutathione S-transferases M1 and T1 is statistically associated with normal CD4+ count in patients diagnosed with HIV/AIDS." (PMID 29795558, 2018). "All the subjects provided stool samples and answered the questionnaires designed to investigate the possible risk factors for Cryptosporidium infection among HIV/AIDS patients and their CD4+ data were also obtained from their clinical records." (PMID 30369995, 2018). "Over time, the continued depletion of CD4 T cells causes an AIDS-defining illness where people become susceptible to a plethora of opportunistic infections." (PMID 29541072, 2018). "In 2016, annual deaths from AIDS was ~29,327, and ~120,000 persons had CD4 counts <200 × 106/mL, at risk of presenting with opportunistic infections and ~240,000 not receiving (free) antiretroviral therapy (ART)." (PMID 29601494, 2018). "Previous studies have shown that the composition and kinetics of T lymphocyte subsets predict infections, and in the setting of HIV and AIDS, it is well established that a low CD4+ cell count is a major risk factor for opportunistic infections." (PMID 30383787, 2018). "Here, we consider treatment of infections with the human immunodeficiency virus (HIV), a pathogen that infects T-helper CD4+ cells of the immune system and can cause acquired immune deficiency syndrome (AIDS)." (PMID 30839858, 2018). "A low CD4+/CD8+ ratio has been linked to greater risk for PML, with a CD4+ T-cell peripheral count less than 200 cells/μl used as an immunological predictor of PML in AIDS patients." (PMID 29410647, 2018). "We sought to analyse epidemiological data and to determine the causes of hospitalization and advanced presentations of HIV/AIDS patients based on CD4+ T‐cell counts from 2013 to 2017." (PMID 29671462, 2018). "Impaired IL-2-producing T cells was one of the first functional defects observed in chronically HIV-1-infected patients, which predicts loss of CD4+ T cells and progression to AIDS." (PMID 29636753, 2018). "In another study, clinical AIDS and immunodeficiency (CD4+ < 200/uL) were also found to be associated with decreased diversity of the enteric microbiome, although the degree of changes depended on the stage of the disease and the success of treatment." (PMID 29933546, 2018). "Unsurprisingly, very low CD4+ count at initiation as well as the presence of an AIDS-defining condition was associated with increased risk of death." (PMID 30568838, 2018). "In particular, when modelling HIV/AIDS progression, Markov models are relatively straight forward to analyse both CD4 stage and death or loss to follow-up within a single model which survival models fail to do." (PMID 29343268, 2018). "Over the next 2–3 years, however, despite the co-expression of HLA-B*27:05 and HLA-B*57:01, progression to AIDS (absolute CD4+ T cell < 200 cells/mm3) occurred rapidly, in association with viral loads increasing to > 105 copies/ml." (PMID 29338738, 2018). "HIV, a single-stranded enveloped RNA virus, primarily infects human CD4+ T cells, macrophages and dendritic cells which ultimately causes acquired immunodeficiency syndrome (AIDS) over time if left untreated." (PMID 30453598, 2018). "Prior infection with CMV is a risk factor for a low CD4 count, progression to AIDS and mortality in HIV patients." (PMID 29686665, 2018). "When analyses were performed separately among adults ≥50 and <50 years, lower CD4 count was still associated with death and treatment modification, AIDS was still predictive of death, and PI‐based regimens remained a risk factor for treatment modification." (PMID 29569354, 2018). "Conditions traditionally associated with late presentation as male sex, older age, low CD4 and AIDS presentation are associated to bad prognosis." (PMID 30362663, 2018). "Some ECs display a progressive loss of CD4+ T cell counts and eventually progress to AIDS over time." (PMID 30050532, 2018).
AIDS (continued). "Clearly CD4 T cells are required since patients with low CD4 counts because of untreated AIDS are at high risk for disseminated infections Patients treat with tumor necrosis factor inhibitors are also at higher risk." (PMID 30179067, 2018). "In the pre-combination antiretroviral therapy era, PML had an approximately 5% incidence in patients with HIV/AIDS, a disease initiated by profound CD4 T cell deficiency." (PMID 30372487, 2018). "We also evaluated the CD4%, as this marker is considered one of the best predictors of AIDS-associated events; a previous study that divided ECs based on CD4% demonstrated different levels of immune activation among the groups." (PMID 30050532, 2018). "CD4+ T-cell deficient patients such as those with AIDS and idiopathic CD4+ T-cell lymphopenia are vulnerable to systemic fungal infections." (PMID 28542595, 2017). "Factors independently associated with PCS scores in our cohort were age, CD4+ cell count <200 cells/mm3, mental comorbidity, military rank, marital status, gender, medical comorbidity, AIDS diagnosis, and baseline enrollment year being 2007." (PMID 28591161, 2017). "Significantly enhanced susceptibility to TB in people suffering from HIV/AIDS or inherited IFNγ deficiencies underlines the critical role of IFNγ-producing CD4+ T cells (IFNγ+CD4+ T cells) in host resistance to Mtb." (PMID 28646367, 2017). "Factors associated with lower PCS scores were age, CD4+ cell count <200 cells/mm3, lower military rank or being civilian/retired, presence of medical and mental comorbidities, AIDS diagnosis, and being married." (PMID 28591161, 2017). "These late-stage infections and cancers associated with a loss of CD4+ T cells define the onset of AIDS that ultimately leads to death." (PMID 29259605, 2017). "This study, together with previous reports of disease progression in HIV-1 infected captive chimpanzees, indicates that animals with high viremia and reduced CD4+ T cell counts are at risk of developing AIDS and should be treated to prevent clinical disease." (PMID 28576126, 2017). "Higher CD4 count, lower viral load, and a prevalent AIDS diagnosis were clinical characteristics associated with delayed ART initiation." (PMID 28700693, 2017). "In conclusion, the CRF01_AE subtype and a lower CD4 count at baseline tend to be associated with the faster progression of HIV/AIDS." (PMID 28484257, 2017). "Old ChRM showed a higher risk of accelerated AIDS development than did young macaques, owing to rapidly elevated plasma viral loads and decreased levels of CD4+ T cells." (PMID 28232735, 2017). "This is consistent with well-established evidence that plasma HIV VL is associated with more rapid declines in CD4 cells and an increased risk of progression to symptomatic disease and AIDS." (PMID 28267790, 2017). "Increased immune activation in patients on long-term suppressive cART has been associated with increased mortality, the occurrence of non-AIDS-defining conditions, and a poorer recovery in CD4+ T cell count." (PMID 29375567, 2017). "It was observed that the greater the severity of infection (AIDS, CD4+ T-cell count <200 cells/μl), the greater the risk of thromboembolic complications." (PMID 28749986, 2017). "All animals were euthanized due to the onset of neurological and/or AIDS like symptoms (diarrhea, weight loss), which coincided with CD4+ T cell numbers of less than 200 cells/μL." (PMID 28787449, 2017). "According to the HIV guidelines in Mozambique in 2013–2014, HIV-infected patients initiated ART if CD4 T-cell counts were ≤350 cells/mm3 or presenting an AIDS-associated disease, features more common at late stages of HIV infection." (PMID 29354131, 2017). "Patients with a lower CD4/CD8 ratio after long-term ART have a higher risk of non-AIDS-related morbidities and mortalities." (PMID 29246197, 2017). "Clinical factors associated with delayed ART included higher CD4 cell count, lower viral load, and a prevalent AIDS diagnosis." (PMID 28700693, 2017).